ENSG00000238440
Synonyms: LOC124903101
Gene: Small nucleolar RNA gene on chromosome 12 (64,355,762 to 64,355,865, reverse strand). Ensembl gene ENSG00000238440.
Gene Ontology:
Biological process: RNA processing
Cellular component: nucleolus
Homologues: Paralogues in human: SNORD13P1 (86% identical), SNORD13 (85% identical), SNORD13D (83% identical), SNORD13E (81% identical), SNORD13P3 (81% identical).